KRAS (KRas proto-oncogene, GTPase)
Diseases named in the same sentence as KRAS in open-access papers (continued):
Sharing a sentence is not in itself a finding about the gene and the disease.
lung cancer (continued). "In lung cancer, KDM4A collaborates with oncogenic KRAS to promote cellular transformation by downregulating tumor suppressor chromodomain helicase DNA binding protein 5 (CHD5)." (PMID 38914477, 2024). "In the KRAS-mutant LUAD setting, Id1 expression, known to provide an aggressive pro-oncogenic phenotype and to enhance the colonization capacity of lung cancer cells, has been shown to correlate with reduced overall survival and poor treatment response." (PMID 38643157, 2024). "We first tested the time-dependent effect of the KRASG12C inhibitor ARS-1620 on the expression of KRASG12C, ERK phosphorylation, accumulation of active KRAS (KRAS-GTP), and the cell cycle of KRASG12C-mutant lung cancer cells." (PMID 38225225, 2024). "Another study on KRAS mutant lung adenocarcinoma identified UHRF1 as a critical target for cardiac glycosides, potent DSB repair inhibitors, in sensitizing KRAS mutant lung cancer to chemotherapy." (PMID 39051184, 2024). "Increased β3, by interacting with galectin-3, thus activating KRAS, RELB, and NF-ΚB pathways, is involved in erlotinib and lapatinib resistance in lung cancer and linsitinib resistance in pancreatic cancer." (PMID 39063187, 2024). "Relevant to this study, treatment of KRASG12C lung cancer cells with sotorasib has been shown to induce the increased expression of AURKA, which then directly interacted with KRASG12C, locking KRAS into an active, KRASG12C inhibitor–insensitive state." (PMID 38639476, 2024). "In lung cancer, for example, de novo activating alterations in EGFR, KRAS, ROS1, ALK, RET, and NTRK rarely coexist." (PMID 38938274, 2024). "To explore the role of YAP/TAZ in regulating the sensitivity of KRAS G12C–mutant cancer cells to KRAS G12C inhibitors, we knocked down YAP or TAZ separately in SW1573, a lung cancer cell line that is highly resistant to KRAS G12C inhibitors." (PMID 39704172, 2024). "However, only the study of KRAS G12C mutation has made a breakthrough with a specific inhibitor AMG510 (Sotorasib) approved by FDA and MRTX849 (Adagrasib) ongoing clinical trials, and the limited success just benefits to a very small number of lung cancer patients." (PMID 38872211, 2024). "Consistent with a previous report, ARS-1620 initially suppressed ERK phosphorylation and accumulation of KRAS-GTP in both H23 and H358 KRASG12C-mutant lung cancer cells." (PMID 38225225, 2024). "Moreover, simultaneous RASSF1A methylation and KRAS mutation shortened survival in patients with NSCLC, suggesting that RASSF1A methylation may synergically promote the growth of lung cancer with KRAS mutation by inhibiting the Hippo pathway, which needs further confirmation." (PMID 38499647, 2024). "In a study aimed at targeting KRAS in lung cancer, HEK293T cells were programmed to simultaneously express KRAS siRNA and Lamp2b, an exosomal membrane protein, coupled with a tumor-homing internalizing RGD (iRGD) peptide." (PMID 39355533, 2024). "First, immunohistochemical interrogation of 89 EGFR-mutant, 51 KRAS-altered, and 46 ALK-rearranged lung cancer specimens unveiled that YY1 was ubiquitously expressed in malignant cells at an elevated level relative to the normal epithelium." (PMID 39604408, 2024). "Using two preclinical syngeneic KRAS-mutant LUAD mouse models, we found that trametinib synergizes with PD-1/PD-L1 blockade to hamper lung cancer progression and increase survival." (PMID 38643157, 2024). "Recently, UHRF1 was identified as a mediator of KRAS-driven lung cancer, whereby knockout of UHRF1 in KRAS mutant cells leads to reduced tumor growth and promotes apoptosis." (PMID 38914477, 2024). "KRAS is one of the most prevalent isoforms among the RAS family, being found in 85% of pancreatic, 45% of colo-rectal, and 30% of lung cancer." (PMID 38528576, 2024). "Consistent with the results in our lung cancer GEMM, degradation of KRASG12V upon administration of dTAGV-1 significantly inhibited tumor growth of PATU-8902 FKBP12F36V-KRASG12V; KRAS–/– cells." (PMID 39718828, 2024).
lung cancer (continued). "The MEK inhibitor trametinib inhibits the expression of SPRY4 in stromal-like KRAS mutant NSCLC, leading to the activation of AKT and ERK signals in stromal-like KRAS mutant lung cancer cells." (PMID 38686189, 2024). "Common signal pathways involved with advanced lung cancer, were epidermal growth factor receptor/Kirsten rat sarcoma/anaplastic lymphoma kinase (EGFR/KRAS/ALK) and C-X-C motif chemokine ligand 12/C-X-C motif chemokine receptor 4 (CXCL12/CXCR4)." (PMID 38711158, 2024). "In this study, by using GEMMs of KRAS-driven NSCLC, we found that the dependence on G6PD is distinct in different subtypes of lung cancer." (PMID 38997257, 2024). "An increase of CPS1 expression and urea cycle metabolites in KRAS and LKB1 co-mutant lung cancer cells increases pyrimidine synthesis and benefits for tumor growth." (PMID 39544365, 2024). "We selected three (KL/K)MUT and three (KL/K)WT lung carcinoma cell lines for further study: The first group included HCC44 and H460 (KRAS/LKB1/KEAP1 triple mutant) along with H1792 (KRAS/KEAP1 double mutant)." (PMID 38949950, 2024). "A recent analysis of the G12D mutant lung cancers demonstrated that the density of CD8+ T cells, the TMB and the tumor cell expression level of PDL1 are lower as compared to other KRAS mutants including G12C." (PMID 38239281, 2023). "However, it should be noted that proliferation and colony formation of lung cancer cells with KRAS mutations may be less affected by PM2.5 exposure than lung cancer cells harboring tEGFR mutations, and AhR has also been reported to suppress KRAS-driven NSCLC." (PMID 37696458, 2023). "In another study, at a concentration of 2 μM, homoharringtonine inhibited the expression of KRAS, ERK, Akt, STAT3, CDK4, and CDK6 in A549 and H1299 lung cancer cells." (PMID 37568796, 2023). "However, the functions of HIF1A-As2 in lung cancer, particularly in KRAS-driven NSCLC, are unknown." (PMID 37041291, 2023). "Thus, immunotherapy for KRAS-mutant lung cancer may show potential." (PMID 37662925, 2023). "Taken together, these results demonstrate that eIF4A is an important therapeutic target in KRAS-mutant NSCLC cells and that suppression of this eIF4F component dramatically sensitizes lung cancer cells to both KRAS G12C and MEK inhibitors." (PMID 37384411, 2023). "The subsequent systematic review focuses on the utilization of LCOs as in vitro models to assess drug sensitivity, encompassing chemotherapeutic agents and targeted drugs against common lung cancer biomarkers such as EFGR, ALK, and KRAS." (PMID 37941550, 2023). "Non‐small cell lung cancers with ERBB2 amplification, MET activation, KRAS G12C, RET, and ROS1 fusion resulted in the second‐highest frequency of recommendations." (PMID 36251535, 2023). "In human lung cancer models UHRF1 knock-out selectively impaired growth and induced apoptosis only in KRAS mutant cells." (PMID 37407562, 2023). "Our study revealed that treatment of A549 human lung cancer cell line with ALUP, BA and LUP significantly increased the expression of let-7 miRNA and reduced the expression of Cyclin D1, KRAS and VEGF levels." (PMID 37845669, 2023). "Recently, two KRAS G12C inhibitors, sotorasib (AMG 510) and adagrasib (MRTX 849), showed excellent anti‐tumor activity in lung cancer." (PMID 36999792, 2023). "We recently showed that lncRNA KIMAT1 modulates KRAS signalling, microRNA biogenesis and tumor metastasis through interactions with the RNA-binding proteins DHX9 and NPM1 in lung cancer." (PMID 37041291, 2023).
lung cancer (continued). "Furthermore, we also discuss the recent data demonstrating how combination therapy can help alleviate KRAS drug resistance in lung cancer, and how new treatment strategies based on evolutionary principles may help minimize or even preclude the emergence of drug resistance." (PMID 38002269, 2023). "In addition, PI4KA tethering to the PM by EFR3 was found to increase the levels of KRAS, the most common human oncogene at the PM and its downstream signaling, thus providing a novel intervention route in KRAS-dependent carcinomas such as pancreatic, colorectal, or lung carcinoma." (PMID 37408244, 2023). "In lung cancer treatment, KRAS is downstream of the EGFR pathway; therefore, tyrosine kinase-based treatment with gefitinib and erlotinib is ineffective when KRAS is constitutively activated." (PMID 35163506, 2022). "Targeted drugs against KRAS-, EGFR- or ALK-driven lung cancer induce apoptosis and pyroptosis simultaneously." (PMID 36411454, 2022). "A previous study in 36,813 Chinese lung cancer patients, focusing on eight key lung cancer driver genes (EGFR, ALK, MET, KRAS, ERBB2, ROS1, RET, and BRAF), revealed a prevalence of 0.03% for P/LP germline mutations." (PMID 35428225, 2022). "DHA decreased the cell viability in H1299, and KRAS-mutant A549 and LLC1 lung cancer cells in a dose-dependent manner, via the EGFR and downstream proteins’ inhibition." (PMID 36547898, 2022). "In H460 lung cancer cells, the evaluation of UA compounds’ influence on MYC and KRAS gene expression gave different results than in colon cells." (PMID 35328482, 2022). "The mechanism accounting for the difference in the number of LDs in lung cancer cells is not known at this moment, but the types of driver mutations seem to play a role, as the number of LDs was comparatively higher in all tested KRAS-mutated cells than in EGFR-mutated cells." (PMID 36293388, 2022). "Furthermore, it has been demonstrated that patients with negative cytological results may benefit from screening for KRAS mutations in BALF cells to help with a lung cancer diagnosis." (PMID 36552956, 2022). "Once a lung cancer is dominated by EGFR-mut cells has a very different immune (low immune infiltration) and extra-cellular matrix than a KRAS-mut lung cancer with high immune infiltration and less structured extra-cellular matrix." (PMID 35061724, 2022). "Small molecule inhibitors of kinases such as MEK, BRAF, EGFR, ALK, and KRAS promoted GSDME cleavage by CASP3 and resulted in lung cancer and melanoma regression." (PMID 35964070, 2022). "Using mouse model recapitulating lung cancers KrasG12D/ZNF24−/− patients, we found that combinational inhibition of KRAS, NF-κB and PD-1 effectively shrank the lung tumor." (PMID 36457047, 2022). "Triple-negative breast cancer (TNBC) and Kirsten rat sarcoma virus (KRAS)-mutant lung cancer have limited therapeutic options, but ABZ has been reported to suppress TNBC- and KRAS-mutant cells." (PMID 36230527, 2022). "More interestingly, the deletion of FOXA1 in KRAS-driven neoplasia derived from alveolar cells resulted in keratinizing squamous cell carcinoma, indicating that FOXA1/2 manipulated the growth of lung cancer in a context-dependent manner." (PMID 36012038, 2022). "This propriety of HDAC1 proved to be successful in knocking down KRAS expression in the colorectal cancer HCT-116 and lung cancer H385 cell line models." (PMID 36139356, 2022). "Besides, deletion of STAT3 could enhance KRAS-driven lung cancer development." (PMID 36619616, 2022). "Taken together, these data indicate that combinational inhibition of NF-κB, KRAS and PD1 are effective to treat KrasG12D/ZNF24−/− lung cancers." (PMID 36457047, 2022).
lung cancer (continued). "Compared with testing other lung cancer driver genes, such as EGFR and KRAS, the application of NGS in the diagnosis of MET alterations is not very efficient, especially for METex14 skipping mutation." (PMID 36212500, 2022). "Our findings provide a direct link between BCL6 and KRAS oncogenic signaling and highlight that BCL6 is an important target for the treatment of KRAS-driven lung cancer." (PMID 36377663, 2022). "We found eight genes relevant to lung cancer (PDGFRB, RET, KRAS, KEAP1, ROS1, STK11, MET and ALK), for which integrating clinical data with our TME features clearly improves the ability to predict mutations in these genes." (PMID 36131239, 2022). "Here, we report a case of a pulmonary invasive mucinous adenocarcinoma harboring KRAS G12D, diagnosed from tumor samples containing a very small amount of tumor cells using next‐generation sequencing (NGS) and the recently developed Lung Cancer Compact Panel." (PMID 35545933, 2022). "As well as identifying iRhom2 as an essential player in KRAS-induced tumorigenesis, these results reveal the existence of a previously unidentified positive feedback loop that maintains RAS activity in lung cancer cells." (PMID 35971826, 2022). "Sequentially, we evaluated the targetable variations detected ability in different samples, including EGFR, ALK, BRAF V600E, KRAS, MET ex14 skipping, RET, ROS1, ERBB2, which have high evidence in lung cancer." (PMID 36167530, 2022). "Among them, the KRAS/MEK pathway has been proven to abrogate the activity of PI3K inhibitors against breast and lung cancer." (PMID 35604910, 2022). "Our study also found that MA, acting as a PLA2 inhibitor, significantly inhibited KRAS expression and the downstream ERK pathway in lung cancer cells, suggesting that MA may inhibit KRAS by suppressing PLA2 and overcome the EGFR-TKI resistance in KRAS- mutated lung cancer cells." (PMID 36712673, 2022). "Dox-dependent induction of DX2 also led to an increase in KRAS levels in DX2-inducible mouse embryonic fibroblasts (MEFs) and H460 lung cancer cells stably expressing Strep-tagged DX2." (PMID 35546148, 2022). "To uncover the link between BCL6 expression and clinical outcomes in KRAS-mutant lung cancer, we further examined BCL6 expression in human LUAD tissue, including KRAS-mutant subgroup (n = 62) and KRAS WT subgroup (n = 67)." (PMID 36377663, 2022). "AMG510 is the first KRAS (G12C) inhibitor in clinical development and treatment and was recently approved by FDA for the lung cancer therapy." (PMID 35785187, 2022). "Those genes are frequently altered in different cancers, including AKT1, EGFR, KRAS, and STK11 in lung cancer and AKT1, BRCA2, ERBB2, and PIK3CA in Breast cancer." (PMID 34906079, 2021). "We noticed that genetic depletion of FGFR1 increased PLK1 activity and PLK1 reduction upregulated FGFR1 in KRAS‐mutant lung and pancreatic cancer cells, suggesting that FGFR1‐ and PLK1‐mediated pathways reciprocate in KRAS‐mutant lung cancer." (PMID 34369083, 2021). "Notably, PDX tumors derived from sample LF09—a lepidic ADC subtype and, therefore, linked to the non-aggressive lung cancer subtype—carried a KRAS oncogenic mutation and preserved the expression of Ki67 through the different passages, thus featuring enhanced aggressiveness." (PMID 34198671, 2021). "Using a mouse model of lung cancer, we demonstrate that the translational repression of DUSP6 by p-eIF2α is an important mechanism of mutant KRAS tumorigenesis." (PMID 34330898, 2021). "There are only few studies dedicated to KRAS and HRAS expression at mRNA level in lung cancer tissue." (PMID 33549031, 2021). "Recently, a KRAS agonist, KRA-533, was identified to suppress mutant KRAS-driven lung cancer in vitro and in vivo, binding the GN binding site to prevent the exchange of GTP to GDP." (PMID 34301278, 2021).
lung cancer (continued). "For lung cancer, we collect the status of the National Comprehensive Cancer Network (NCCN) recommended biomarkers: EGFR, ALK, BRAF, ROS1, KRAS, RET, NTRK and PD-L1." (PMID 33572220, 2021). "Recent development of KRAS isoform-specific inhibitors highlights these expectations, as KRASG12C blocker was found to drive antitumor immunity in a lung cancer model." (PMID 33674596, 2021). "Some lung cancer‐related genes, such as EGFR, ALK, and KRAS, are usually used for targeted NGS in early‐stage lung cancer." (PMID 33200540, 2021). "In addition, we observed that pyrvinium could cause the accumulation of ROS in Molm13 cells, and it has been reported to selectively trigger the ROS release and mitochondrial membrane depolarization, as well as inhibit aerobic glycolysis in KRAS-mutant lung cancer cells." (PMID 34944685, 2021). "KRAS activates lipogenesis, which is related to the specific induction of FAS, and this activation leads to different proteomics and lipid signatures in lung cancer cells." (PMID 33801246, 2021). "Consistent with the previous results with IEC6 rat intestinal epithelial cells and colorectal and lung cancer cells, the MEK inhibitors PD184161 and U0126 and siRNAs for β-catenin and KRAS decreased ARL4C expression in S2-CP8 and PANC-1 cells." (PMID 34590580, 2021). "The currently available literature indicates that exosomal miR-210 is involved in the regulation of various lung cancer-related signaling molecules and pathways, including STAT3, TIMP-1, KRAS/BACH2/GATA-3/RIP3, and PI3K/AKT." (PMID 34440422, 2021). "Having proved these pharmacological treatments significantly affect tumor growth of human mutant-KRAS cells in vivo, we tested the clinical-grade PTC596 efficacy in the KP model of lung cancer." (PMID 33854168, 2021). "Alterations in KRAS have been seen in 30% of NSCLC cases, which is the major (80%) form of lung cancer." (PMID 34830024, 2021). "Several studies including murine models have revealed a link between oncogenic KRAS and EGFR and increased canonical NF-κB activity in mouse lung cancer models and human lung epithelial cells, and the induction of an inflammatory response in lung tumours." (PMID 34503110, 2021). "Our data support advancing the use of CA170 for lung cancer, and it indicates the potential of combining CA170 with the KRAS vaccine to achieve even better anti-tumor efficacy in lung cancer patients." (PMID 34302042, 2021). "For example, co-activation of KRAS and MYC in a mouse lung cancer model leads to the production of CCL9 and IL-23." (PMID 33859752, 2021). "The current study expanded these findings to a third human NSCLC-derived orthotopic lung cancer model using the EGFR and KRAS wild-type H358 cell line." (PMID 33860729, 2021). "According to Sacher and colleagues (2016), an application of ddPCR in plasma of individuals with lung cancer appeared to have a positive predictive value of 100% for EGFR 19 del and 100% for KRAS." (PMID 34571783, 2021). "Our findings are in line with a previous study demonstrating that activated KRAS proto-oncogene and insulin-like growth factor 1 signaling induce MDM4 expression at least partially via ELK1 in breast, colon, and lung cancer cells." (PMID 33429878, 2021).